URAHP (urate (hydroxyiso-) hydrolase, pseudogene)
Synonyms: URAH
Gene: Transcribed unprocessed pseudogene on chromosome 16 (90,043,914 to 90,047,597, reverse strand). Ensembl gene ENSG00000222019.
Diseases named in the same sentence as URAHP in open-access papers:
URAHP is named in the same sentence as 3 diseases in open-access papers, as found by Europe PMC text mining. Sharing a sentence is not in itself a finding about the gene and the disease. The quoted sentences say what the papers report.
melanoma (1 paper, 2024). A malignant, usually aggressive tumor composed of atypical, neoplastic melanocytes. "For example, genes in cluster 2 (SPIRE2, SPATA2L), 3 (OCA2, DBNDD1, FANCA, GAS8) and 4 (URAHP, DEF8, CPNE7, MC1R) underlie the associations between melanoma and pigmentation traits." (PMID 38308491, 2024).
cancer (1 paper, 2021). A tumor composed of atypical neoplastic, often pleomorphic cells that invade other tissues. "CRY1 has been implicated as a prognostic marker progression and survival in CLL and other types of cancer, however, the role of URAHP, MID1IP1, and CLEC3B has not been explored in CLL." (PMID 34187466, 2021).
URAHP also shares sentences with these, for which no sentence is quoted: skin cancer (1 paper).